IL10 (interleukin 10)
Diseases named in the same sentence as IL10 in open-access papers (continued):
Sharing a sentence is not in itself a finding about the gene and the disease.
Chagas disease (continued). "The authors also suggested that captopril increased the monocyte infection involved in Chagas disease by induction of interleukin 17 (IL-17) and inhibition of IL-10 production." (PMID 29765306, 2018). "Several studies regarding the role of IL-10 in the progression of experimental and human Chagas’ disease have been conducted." (PMID 24260222, 2013). "In this regard, it has been reported that peripheral blood mononuclear cells isolated from patients in the indeterminate phase of Chagas’ disease produce higher levels of IL-10 than those isolated from patients with chronic cardiomyopathy." (PMID 24260222, 2013). "Our study reports the first evidence that T. cruzi up- regulates SOCS-3 expression and highlights the relevance of IL-10 in the modulation of pro-inflammatory response of cardiomyocytes in Chagas’ disease." (PMID 24260222, 2013). "In this context, IL-10 acts as a double-edged sword protecting the host from immune-mediated injury while also potentially favoring parasite persistence and contributing to the chronicity of Chagas disease." (PMID 41007442, 2025). "The present study was designed to determine whether SNPs in IL12B, IL10, IFNG and IL4, key genes involved in the promotion and control of Th1 differentiation and IFN-g production to T. cruzi, are associated with Chagas disease outcome." (PMID 32733459, 2020). "Moreover, it has been reported that peripheral blood mononuclear cells isolated from patients in the indeterminate phase of Chagas disease produce higher levels of IL-10 than those isolated from patients with chronic cardiomyopathy." (PMID 31214200, 2019). "Previously, studies have reported that monocytes could be involved in the downregulation of the immune response by the production of the anti-inflammatory cytokine IL-10 in Chagas disease." (PMID 29599775, 2018). "In Chagas disease, while the cytokine IL-12 leads to the activation of a Th1-lymphocyte-mediated response, the cytokine IL-10 contributes to the inhibition of IL-12 production by monocytes, lymphocytes, and dendritic cells, leading to regulation of immune response." (PMID 29599775, 2018). "The notion concerning the manipulation of Treg cells either by antibodies to CD25, IL-2, and/or IL-10 might open up a new avenue for therapeutic strategies in Chagas' disease." (PMID 27242702, 2016). "The evidence regarding the role of IL-10 in the evolution of human Chagas’ disease is less clear." (PMID 24260222, 2013). "Our results are in agreement with the literature because several studies using acute experimental models of infection or in humans have reported the critical role of TNF-α, IFN-γ and IL-10 in modulating the immune response in the acute phase of the Chagas disease." (PMID 23951243, 2013). "Thus, the identification if the contact cell-cell through CTLA-4 to Treg cells produces IL-10 is crucial to understanding their role in Chagas' disease." (PMID 21655351, 2011). "It has been demonstrated that patients with the indeterminate clinical form of Chagas disease display a predominantly modulatory immune environment, with higher production of the anti-inflammatory cytokine IL-10 and IL-17, which are produced by monocytes (IL-10) and T cell subsets (IL-10 and IL-17)." (PMID 26147698, 2015). "On a Brazilian population, including hundred fifty-five patients in the chronic phase and 43 individuals without Chagas disease, the polymorphism IL10-1082G/A, which correlates with lower expression of IL-10, was associated with the development of Chagas disease cardiomyopathy." (PMID 25210230, 2014). "This resulted in a low and significant TNF-α/IL-10 ratio that may have contributed to the lower mortality rate and to the higher survival time observed among coinfected animals In fact, there are several reports on the immuno-modulatory role of IL-10 in infectious diseases including Chagas disease." (PMID 20967289, 2010).
Chagas disease (continued). "EBI3/IL-27B dampens IFN-γ driven inflammation by inducing IL-10-producing Tr1 cells, and plasma levels of EBI3/IL-27B are higher in indeterminate/ASY Chagas disease patients than CCC patients." (PMID 40297326, 2025). "Cardiac patients exhibited higher mRNA expression of IFN-γ, TNF-α and lower mRNA expression of IL-10, Foxp3, AHR, and GATA-3 than those with the indeterminate clinical form of Chagas disease." (PMID 27115869, 2016). "The expressions of different cytokines (IL-10, IFN-γ, TNF-α, IL-6, IL-1β) were evaluated in the plasma of healthy individuals and patients with different forms of Chagas disease." (PMID 24603474, 2014). "In this investigation we first evaluated the production of IFN-γ, TNF-α, IL-10 and IL-17 in PBMC obtained from groups of Chagas' disease patients and in a group of benznidazol-treated individuals." (PMID 22545173, 2012). "A recent study found higher levels of interferon-gamma, tumor necrosis factor-alpha, interleukin-10 and CCL3 in the myocardium of hamsters exhibiting acute symptoms of Chagas disease, when compared to asymptomatic animals." (PMID 20559542, 2010). "Our recombinant plasmids used in the present study were also used in a prophylactic vaccination scheme for Chagas disease in canine models in previous studies, where the results indicated that vaccination with pBCSSP4 significantly increased the IFN-gamma and IL-10 levels at 9 months postinfection." (PMID 32455143, 2020). "In Chagas disease, IL-10 seems to be part of a regulated, nonpathogenic immune response in patients without cardiomyopathy." (PMID 27242702, 2016). "CCC patients show an increased number of CD4+ and CD8+ IFN-γ-producing T cells in the peripheral blood, with reduced numbers of IL-10-producing CD4+CD25+ regulatory T cells and CD4+CD25+ FoxP3+ regulatory T cells as compared with patients in the ASY form of Chagas disease." (PMID 25210230, 2014). "However, the same authors reported later in a study that patients with the indeterminate form of Chagas' disease exhibited a higher frequency of CD4+CD25high T cell expressing Foxp3 and IL-10 as compared to those individuals with cardiomyopathy." (PMID 22545173, 2012). "In an attempt to better characterize these cells in Chagas' disease, we investigated whether CD25High CD4+ Treg in the peripheral blood of chagasic patients are IL-10 producers." (PMID 21655351, 2011). "The most studied cytokines in Chagas disease are IFN-γ and IL-10." (PMID 19742301, 2009). "P21 also has the capacity to induce an immune response through IL-4, IL-10, and IFN-γ production in T. cruzi infection, contributing to the control of parasite proliferation in the host organism and at the same time triggering the pathogenesis of Chagas disease." (PMID 37915581, 2023). "It was noteworthy that Chagas disease hosts develop, upon homologous T. cruzi antigen recall in vitro, a prominent pro-inflammatory response involving IFN-γ (NK-cells and T-cells) together with TNF (monocytes, NK-cells, T-cells and B-cells) modulated by IL-10 from monocytes and B-cells." (PMID 28225764, 2017). "Also, TGF-β and IL-10, which are not inflammatory cytokines but do play key roles in Chagas disease, were induced by rTcHMGB." (PMID 28178282, 2017). "IL-10 was the most important anti-inflammatory cytokine studied in the Chagas disease, and it has been shown that NON-CARD patients display higher levels of IL-10 in comparison to cardiac patients." (PMID 24608170, 2014).
endothelial dysfunction (57 papers, 2010 to 2026). In vascular diseases, endothelial dysfunction is a systemic pathological state of the endothelium (the inner lining of blood vessels) and can be broadly defined as an imbalance between vasodilating and vasoconstricting substances produced by (or acting on) the endothelium. "In an IL-10-deficient mouse model, age-associated endothelial dysfunction occurs earlier with IL-10 deficiency, and IL-10 protected the age-associated increase in the expression of IL-6, a pro-inflammatory cytokine." (PMID 32824387, 2020). "Our findings in this study indicate that the presence of IL-10 deficiency results in the appearance of prominent endothelial dysfunction at an earlier age." (PMID 24400151, 2013). "Moreover, changes in cytokine levels, such as IL-6 (interleukin 6), IL-10 (interleukin 10), and IL-13 (interleukin 13), are associated with treatment-related toxicities, notably fatigue and endothelial dysfunction." (PMID 40136656, 2025). "Also, IL-10 plays a role as an anti-inflammatory cytokine, besides associating with longevity, vascular protection, and improvement of endothelial dysfunction." (PMID 36211483, 2022). "Data from vascular tissue suggest that changes in expression of NADPH oxidase and IL-6 might contribute to the observed endothelial dysfunction in old IL-10-deficient mice." (PMID 24400151, 2013). "IL-10 is a potent anti-inflammatory cytokine that normally maintains mucosal homeostasis and protects against endothelial dysfunction." (PMID 41515269, 2026). "Regulatory T cells (Tregs) inhibit endothelial dysfunction through the secretion of IL-10 and TGF-β, suppress the expression of pro-inflammatory factors, maintain vascular homeostasis, and secrete VEGF to promote vascular repair following injury." (PMID 41034706, 2025). "Strikingly, incubation of aortic rings with an IL-10 neutralizing antibody targeting the key cytokine released by Tregs that inhibits NADPH oxidase abolished the improvement in endothelial dysfunction induced by microbiota from LC40-treated SHR in WKY rats." (PMID 41254951, 2025). "Higher levels of TMAO lead to endothelial dysfunction, oxidative stress, a decrease in anti-inflammatory cytokine Il-10, and increased inflammation." (PMID 37109497, 2023). "It is well stablished that IL-10 released by Treg improves endothelial dysfunction through inhibition of vascular NADPH oxidase activity improving vascular oxidative stress, which contributes to reduce blood pressure in IMQ-treated mice." (PMID 34444829, 2021). "In particular, inhibition of IL-10, known to protect from carotid atheromatous disease and coronary calcification, led to endothelial dysfunction and vascular inflammation of carotid arteries in IL-10 knockout aged mice according to experimental findings." (PMID 32582337, 2020). "Intriguingly, IL-10 is elevated in SLE patients, and IL-10 potentiates IFN-I-induced endothelial dysfunction." (PMID 33117403, 2020). "Others are associated with anti-inflammation (IL-10 and TRAIL) or endothelial dysfunction (CD40 ligand, EGF)." (PMID 33138839, 2020). "Subsequently, they found that IL-4 treatment and IL-4/ interleukin 10 (IL-10) co-treatment was able to significantly reduce blood pressure and prevent endothelial dysfunction in a TLR3-induced PE mouse model." (PMID 32337535, 2020). "The receptor expression has also been observed in endothelial cells, which provides the structural evidence for IL-10 to not only counteract pro-inflammatory cytokines but also potentially inhibit endothelial dysfunction directly." (PMID 25387998, 2014). "Our findings suggest a novel role for IL-10 to protect against age-related increases in expression of IL-6, oxidative stress, and endothelial dysfunction." (PMID 24400151, 2013). "Overall, our findings provide direct evidence that IL-10 plays a major role to suppress age-induced oxidative stress, increases in IL-6 expression, and endothelial dysfunction." (PMID 24400151, 2013).
endothelial dysfunction (continued). "Our findings indicate that genetic deficiency in IL-10 enhanced expression of IL-6 and accelerated endothelial dysfunction suggesting IL-10 normally protects against age-induced endothelial dysfunction." (PMID 24400151, 2013). "Of note, a reduction in IL-10 levels contributes to endothelial dysfunction." (PMID 39273381, 2024). "In addition, it seems to downregulate the anti-inflammatory IL-10 and nitric oxide (NO) expression and to increase reactive oxygen species (ROS) generation, then favouring endothelial dysfunction." (PMID 37111513, 2023). "Ang II-induced endothelial dysfunction was exacerbated in IL-10 KO mice (IL-10−/−)." (PMID 35502169, 2022). "In addition, it has been suggested that IL10 played an important role in inhibiting endothelial dysfunction in endotoxemia induced by lipopolysaccharide (LPS)." (PMID 35015384, 2022). "However, the effects of macrophages with high expression of IL10 on endothelial dysfunction were not fully understood." (PMID 35015384, 2022). "Whether endothelial dysfunction occurs when IL-10 protection is missing by a longer time of feeding high-fat diet or in the presence of a more pronounced impairment of glucose metabolism is unknown and needs further investigation." (PMID 28466012, 2017). "Il-10, on the other hand, has an anti-inflammatory role and may protect against age-related increases in levels of Il-6, oxidative stress, and endothelial dysfunction." (PMID 27270459, 2016). "It has been suggested that increases in Il-10 might protect against age-related increases in Il-6, oxidative stress and endothelial dysfunction, and confer protection for the immune system against the inflammatory stress response." (PMID 27270459, 2016). "Furthermore, it is demonstrated that IL-10 protects against age-related endothelial dysfunction by the inhibition of oxidative stress." (PMID 25387998, 2014). "Furthermore, IL-10 prevents the impairment of endothelial dysfunction induced by elevated levels of C-reactive proteins." (PMID 25387998, 2014). "In these studies, we tested the hypothesis that interleukin-10 (IL-10), a potent anti-inflammatory cytokine, protects against aging-induced endothelial dysfunction." (PMID 24400151, 2013). "In this study, we examined the hypothesis that IL-10 normally protects against endothelial dysfunction during aging." (PMID 24400151, 2013). "While this manuscript was in preparation, a report appeared suggesting that endothelial dysfunction occurs in older IL-10-deficient mice (but not wild-type) via a mechanism that involves cyclooxygenase and vasoconstrictor prostanoids." (PMID 24400151, 2013). "Genetic deficiency in IL-10 did not alter vascular function in adult mice, but greatly increased endothelial dysfunction in carotid arteries in old mice." (PMID 24400151, 2013). "Th1 response, not counteracted by an increase of anti-inflammatory IL-4 and IL-10 production, may contribute to tissue damage, endothelial dysfunction, and systemic inflammation." (PMID 24324294, 2013). "Therefore, we proposed that IL10 in the supernatant of IL10‐eM was primarily responsible for protective effects against LPS‐induced endothelial dysfunction; however, exosome and cytokine secreted by macrophage may also play an important role in this process." (PMID 35015384, 2022). "Mechanistically, Ang II leads to endothelial dysfunction by increasing gp91phox (NOX2) expression, which is a subunit of NADPH oxidase, while IL-10 inhibits this response by normalizing NADPH oxidase protein expression." (PMID 25387998, 2014). "In this study, we used lentiviral vectors to construct RAW264.7 macrophages engineered to overexpress IL10 (IL10‐eM) and investigated the effects of the IL10‐eM supernatant on LPS‐induced endothelial dysfunction using a noncontact coculture system." (PMID 35015384, 2022).
endothelial dysfunction (continued). "Its correlation with serum levels of biological markers that could participate in endothelial dysfunction pathways such as NO3−/NO2− ratio, NO2−, citrulline, TNFα, IL-1, IL-6, IL-10, IL-8, osteopontin, ICAM, VCAM, and NO3−/NO2− was determined." (PMID 30246778, 2018). "Accordingly, higher levels of IL-10 and decreased levels of IL-1β, after VNS in our model, could have decreased hemorrhage induced endothelial dysfunction and also contributed to better hemostasis." (PMID 25243020, 2014).
acute pancreatitis (56 papers, 2006 to 2025). An acute inflammatory process that leads to necrosis of the pancreatic parenchyma. "Research has confirmed that IL-10 can alleviate the acute pancreatitis and reduce the risk of post-ERCP pancreatitis." (PMID 40991678, 2025). "Inflammatory factors, such as IL-2, IL-6, and IL-10, are closely associated with acute pancreatitis." (PMID 38424643, 2024). "IL-10 gene polymorphism contributes to the development of acute pancreatitis." (PMID 36837523, 2023). "We confirmed that CRP and elastase analyzed on the third day of admission, in addition to the evaluation of IL-6, IL-8, IL-10, and sTNFr on the first day, represent a valuable diagnostic tool in the assessment of severity and course of disease in patients with acute pancreatitis." (PMID 23476635, 2013). "Research is lacking in this area but, in contrast to our findings, a randomised double-blind trial in adults with acute pancreatitis showed increased IL-10 levels in those administered enteral nutrition vs. those who received parenteral nutrition." (PMID 40661891, 2025). "Studies in Chinese population suggest a correlation between IL-10 and acute pancreatitis occurrence." (PMID 38881734, 2024). "IL-10 is a potent anti-inflammatory and anti-fibrotic factor that demonstrates strong efficacy in liver inflammation and acute pancreatitis." (PMID 38255213, 2024). "Serum levels of interleukin (IL)‐1β, IL‐5, IL‐6, IL‐8, IL‐10, IL‐17, and tumor necrosis factor‐α were significantly higher in the severe acute pancreatitis (SAP) group than in the non‐SAP group (p < .05)." (PMID 38411379, 2024). "IL-1β, TNF-α, and IL-10 levels in the acute pancreatitis group were significantly increased when compared to the control negative group." (PMID 38333760, 2024). "Ali and Madkour also stated that the IL-10 level in the melatonin pretreatment of rats with acute pancreatitis was significantly increased." (PMID 38333760, 2024). "The TNF-α, IL-1β, and IL-10 increased significantly in rats of the pancreatitis group of this study compared to healthy rats, they are considered indicators for acute pancreatitis and this finding is consistent with the findings of other authors." (PMID 38333760, 2024). "Serum IL-1β, IL-6 and IL-10 concentrations have been shown to increase after 6 to 12 h of severe acute pancreatitis in pigs." (PMID 37175426, 2023). "IL-10 can reduce the severity of acute pancreatitis in animal models, furthermore, it has been shown that the preventive administration of IL-10 can reduce the risk of post-ERCP pancreatitis." (PMID 37881430, 2023). "Further, increased serum levels of IL-10 are found in patients with severe traumata as well as in patients with severe acute pancreatitis." (PMID 37881430, 2023). "Previous studies showed that IL10 decreased the permeability of BBB in the severe acute pancreatitis model and prevented microvascular protein leakage." (PMID 35015384, 2022). "In a model of cerulean-induced acute pancreatitis, a severe increase of fibrosis was observed in IL-10 knockout mice compared to WT45, together with increased TGF-β1 plasma levels in pancreatic cells." (PMID 30315190, 2018). "One study showed that the infusion of rat BM-MSCs increased the expression of anti-inflammatory cytokines, such as IL-10, following acute pancreatitis." (PMID 29743979, 2018). "Blocking endogenous IL-10 production by pretreatment with an anti-IL-10 monoclonal antibody increased the severity of acute inflammation suggesting a protective role of endogenous IL-10 in acute pancreatitis." (PMID 27314021, 2016). "Serum levels of anti-inflammatory molecules, such as IL-10, IL-1β receptor antagonist, and soluble IL-2 receptor (aIL-2r), are also significantly higher in acute pancreatitis." (PMID 27642079, 2016). "IL-10 levels were shown to be upregulated by Sonic hedgehog expression in the mouse model of cerulein-induced acute pancreatitis." (PMID 27314021, 2016).